DLL4 (delta like canonical Notch ligand 4)
Diseases named in the same sentence as DLL4 in open-access papers (continued):
Sharing a sentence is not in itself a finding about the gene and the disease.
ovarian carcinoma (27 papers, 2014 to 2025). A malignant neoplasm originating from the surface ovarian epithelium. "In the ovarian cancer, Dll4 and Notch 1 were associated with VEGFR1 and VEGFR2 expression respectively, and impacted microvessel density." (PMID 32014047, 2020). "In line, strong expression of Dll4 in ovarian cancer was associated with poor patient prognosis whereas low Dll4 expression correlated with responsiveness to anti-VEGF therapy." (PMID 26755662, 2016). "Other investigators observed Dll4 overexpression in tumor and endothelium in 72% of ovarian cancer samples analyzed by IHC, and increased Dll4 levels were associated with worse overall survival when compared to samples with low Dll4 expression." (PMID 25366565, 2014). "The authors utilized anti-human Dll4 (OMP-21M18) and anti-murine Dll4 to block Notch signaling and found that anti-Dll4 treatment was broadly efficacious in these ovarian cancer models, significantly inhibiting tumor growth." (PMID 35406423, 2022). "The Notch ligands Dll4 and Jagged 1 play key roles in the ovarian cancer resistance to anti-VEGF therapy and platinum." (PMID 33802884, 2021). "Dll4, Notch 1, Notch 3 or Jagged 1 are overexpressed in ovarian cancer suggesting that Notch signaling is primordial in ovarian cancer." (PMID 32014047, 2020). "Enoticumab, binding human Dll4 and disrupting Notch-mediated signaling, had antitumor activity in molecular- and angiogenesis-relevant scenarios in ovarian cancer and other solid tumors." (PMID 33425722, 2020). "In preclinical ovarian cancer models, we have shown that dual targeting of DLL4 and VEGF exhibits superior anti-tumor effects." (PMID 29560266, 2018). "A bispecific DLL4/VEGF (OMP-305B83) antibody is also in phase Ib investigation with paclitaxel in ovarian cancer (ClinicalTrials.gov identifier: NCT03030287)." (PMID 29560266, 2018). "Down-modulation of the Notch ligand Dll4 in combination with anti-VEGF therapy results in a greater tumor growth inhibition than with each agent alone in ovarian cancer models." (PMID 29270405, 2017). "Demcizumab (OMP-21 M18), monoclonal antibody targeting Dll4, is under phase Ib/II clinical development in ovarian cancer patients (NCT01952249)." (PMID 28284219, 2017). "Enoticumab (REGN421) is an anti-DLL4 antibody that has been used to target advanced solid tumors with overexpression of DLL4 (such as ovarian cancer)." (PMID 28356914, 2017). "The over expressions of Dll4, Notch 1, Notch 3 or Jagged 1 suggest that Notch signalling plays a key role in angiogenesis in ovarian cancer." (PMID 28284219, 2017). "Blockage of DLL4 in an orthotopic mouse model of ovarian cancer reduced tumor weights up to 82%." (PMID 35205828, 2022). "Dll4 was administered endothelial and cancer sections of ovarian cancers and its appearance was not linked to grade and extent of cytoreduction." (PMID 35406423, 2022). "Delta-like ligand 4 (Dll4), one of the Notch ligands, is overexpressed in ovarian cancer." (PMID 36275669, 2022). "Taken together, TSE1 might be a potential candidate compound for improving platinum-resistant ovarian cancer treatment via Dll4/Jagged1-Notch1-Akt-HIF-1α axis." (PMID 33802884, 2021). "In addition to targeting Jagged 1 gene, Dll4-notch pathway is another therapeutic target for ovarian cancers." (PMID 28284219, 2017). "Moreover, it has been also reported that high Dll4 expression is predictive of favorable clinical response to anti-VEGF regimen in ovarian cancer." (PMID 29270405, 2017). "Thus, targeting Dll4 in combination with VEGF inhibition potentially improves outcome of ovarian cancer treatments." (PMID 28284219, 2017). "In a phase I human study (NCT00871559) in patients with advanced ovarian cancer, Enoticumab (REGN421), a Delta-like ligand 4 (Dll4) monoclonal antibody that disrupts Notch-mediated signaling was shown to be a safe agent." (PMID 36437919, 2022).
ovarian carcinoma (continued). "Twenty-eight specimens of human ovarian carcinoma, 18 of benign ovarian and 20 of healthy ovarian tissues were subjected to immunohistochemical analysis for VEGF, VEGFR1, and VEGFR2, Dll4, Notch1, and Notch3 expression." (PMID 35406423, 2022). "Another blocking DLL4 antibody, enoticumab, (REGN1035) showed potent anti-tumor activity against renal cell carcinoma and ovarian cancer." (PMID 34680255, 2021). "Two humanized DLL4 antibodies—enoticumab (REGN421) and demcizumab (OMP-21M18)—have shown preliminary anti-tumor activity in ovarian cancer and other solid tumors in phase I studies." (PMID 29560266, 2018). "Dual blockade of Dll4 and VEGF markedly reduced ovarian cancer cell growth." (PMID 36275669, 2022). "The anti-DLL4 antibody demcizumab in combination with paclitaxel showed some signs of clinical benefit (CBR 42% expressed as PR and SD) and acceptably manageable toxicity in patients with recurrent platinum-resistant ovarian cancer in a phase Ib trial." (PMID 34680255, 2021). "Antibodies against the Notch ligand DLL4 have been tested clinically against tumor angiogenesis, but are unlikely to block Notch3 signaling, which appears to be activated by the ligand JAG1 in ovarian cancers where Notch3 signaling has not become ligand-independent." (PMID 32525899, 2020).
glioma (20 papers, 2012 to 2025). A benign or malignant brain and spinal cord tumor that arises from glial cells (astrocytes, oligodendrocytes, ependymal cells). "Various studies have demonstrated increased expression of distinct components of Notch signaling pathway (such as Notch1, Notch2, Dll1, Dll4 and Jag1) and Notch target genes (Hey1, Hey2, Hes1) in glioma cell lines or primary human glioma samples including GBM." (PMID 36010607, 2022). "Two key ligands mediate Notch paracrine receptors in glioma stem cells (GSCs), DLL4, and JAG1, expressed in epithelial cells (ECs)." (PMID 36643842, 2021). "According to previous observations, overexpression of DLL4 in glioma connective tissue reduces vascular density, improves vascular collapse, reduces intra-tumor hypoxia and necrosis, and ultimately prevents tumor growth." (PMID 36643842, 2021). "The same effect of DLL4-Notch signaling has been also observed in gliomas where it was shown that inhibiting the DLL4-Notch signaling pathway increases the degree of vessel sprouting inside the tumor." (PMID 33036204, 2020). "In glioma cells, activation of Notch1 by DLL4 stimulation or overexpression of NICD induces AKT phosphorylation, promoting the migration and invasion of the cells." (PMID 31057403, 2019). "Combined temozolomide and sunitinib treatment leads to selection of large, high-flow, therapy-resistant glioma vessels by aggravating pericyte-mediated resistance mechanisms via angiopoetin–Tie 2 and delta-like-4 (Dll4)/notch signaling." (PMID 29987450, 2018). "Dll4 expressing gliomas have been shown to be resistant towards anti-VEGF therapy by activating different angiogenesis-related pathways leading to large, resistant microvessels." (PMID 29987450, 2018). "Recently, it was shown that the modulation of Dll4/Notch by the extracellular matrix (ECM) protein fibulin-3 promotes angiogenesis in high-grade gliomas." (PMID 26755662, 2016). "Furthermore, high expression of DLL-4 has been shown to be correlated with glioma angiogenesis, and Notch activation via gp130/STAT3 signaling confers resistance to chemoradiotherapy." (PMID 37284062, 2023). "Reis and co-workers showed that forced activation of canonical Wnt signaling in GBM endothelia, up-regulated by glioma-derived Wnt1, increased Dll4 (Delta-like 4) expression and induced Notch signaling, leading to an angiogenic blockage and quiescence of endothelial cells." (PMID 36010607, 2022). "ELTD1 has emerged as an angiogenic biomarker, co-regulated with other angiogenic factors, such as VEGF, NOTCH1, and DLL4.113,114ELTD1 is transcriptionally upregulated in blood vessels of high-grade glioma tumors compared to vessels from low-grade gliomas and from nonmalignant control tissue." (PMID 33959717, 2021). "In malignant gliomas, EFEMP1 secreted by glioma cells could activate DLL4-Notch signaling to induce pro-angiogenic behavior and promote glioma cell motility and invasion." (PMID 27351229, 2016). "This protein plays an important role in angiogenesis and blocking the Dll4-Notch interaction (by overexpression of a soluble Dll4-Fc decoy peptide) enhanced vascular density and angiogenic sprouting in tumors derived from the rat glioma line C6." (PMID 25601901, 2014). "To clarify whether NOTCH1 is involved in PDGF‐D‐mediated EMT in glioma cells, we activated NOTCH1 in the PDGF‐DKD LN18 cells with Dll4 and inhibited NOTCH1 cleavage in the PDGF‐DOE U87 cells using DAPT." (PMID 40530904, 2025). "Interestingly, we observed a significantly lower expression of genes such as PDGFA, FGFR1, DLL4, and VEGFA in glioma patients with a higher TMIGD2 profile." (PMID 37261362, 2023). "This is due to the roles of aberrant activation of Notch components in GBM, such as overexpression of DLL-4 and JAG-1 were detected in GBM endothelial cells and promoted the maintenance and differentiation of glioma stem cells via activating the down-stream Hes1 in tumor cells." (PMID 37284062, 2023).
glioma (continued). "Since Dll4 has been primarily detected in glioblastoma vasculature and not in glioma cells, targeting Dll4 by neutralizing antibodies is considered a potential anti-angiogenic tumor therapy." (PMID 23143192, 2012). "Consistent with this, PDGF‐D knockdown or overexpression in glioma cells led to corresponding changes in the expression of NOTCH1 protein, and NOTCH1 activation using Dll4 reversed the suppressive effects of PDGF‐D knockdown on the migration and invasion of LN18 cells." (PMID 40530904, 2025).
glioblastoma (18 papers, 2012 to 2025). The most malignant astrocytic tumor (WHO grade IV). "Dll4 over-expression in tumour cells in a glioblastoma model caused substantial vessel enlargement at the expense of branching." (PMID 27074663, 2016). "DLL4 was identified as ligand of Notch1 in hepatocellular carcinoma, Notch4 in glioblastoma and Notch3 in melanoma." (PMID 39951484, 2025). "DLL4-overexpressing human glioblastoma cell lines, treated with Bevacizumab, displayed a clear antiangiogenic effect of DLL4 towards the VEGF receptor inhibitor." (PMID 35163601, 2022). "This is further supported by another study demonstrating that mouse DLL4 or JAG1 are expressed in glioblastoma cells and reduced tumor cell proliferation in vitro, but stimulated tumor growth in vivo by modulating angiogenesis." (PMID 33430387, 2021). "Mouse DLL4 or JAG1 expressed in glioblastoma cells decreased tumour cell proliferation in vitro but promoted tumour growth in vivo." (PMID 28445154, 2017). "Cellular migration and invasion, which were induced by DLL4, could be inhibited by either β-catenin or a p50 inhibitor in glioblastoma U87MG and U251 cells." (PMID 35368876, 2022). "To investigate the implications of Dll4/Notch signalling and behavior synchronization between endothelial cells for vascular patterning in tumours, we analyzed dll4 mRNA and protein expresion together with collagen IV deposition in a mouse syngeneic glioblastoma model (GBM)." (PMID 27074663, 2016). "Another example of GSLCs in a hypoxic environment regulated glioblastoma chemoresistance by upregulating JAG1 and DLL4." (PMID 38324181, 2024). "Some studies reveal a role for DLL4 in tumorigenesis in several cancers, including T acute lymphoblastic leukemia (T-ALL), and glioblastoma etc.." (PMID 31996265, 2020). "Immunohistochemistry analyses for DLL4/JAG1 expression and microvascular formation of glioblastoma tumor tissue show enhanced expression of both Notch ligands in tumor vasculature and demonstrate a clear correlation with poor outcome in glioblastoma." (PMID 33430387, 2021). "These tracers target membrane proteins whose expression is altered in glioblastoma (including the EGFR, DLL4, EPHA2, CD47, AC133 antigen, and MT1-MMP): several components of the tumor microenvironment including vessels, macrophages, and extracellular matrix proteins." (PMID 35008238, 2021). "Thus, DLL4 and JAG1 may have an inverse effect on tumor angiogenesis in glioblastoma." (PMID 33430387, 2021).
colorectal cancer (15 papers, 2009 to 2025). A primary or metastatic malignant neoplasm that affects the colon or rectum. "A high level of DLL4 is associated with a reduced efficacy of bevacizumab in advanced colorectal cancer." (PMID 36428773, 2022). "In conclusion, both Notch receptors and ligands are abnormally expressed in colorectal cancer and Notch-3, Jagged-1 and Dll-4 are associated with tumor metastasis." (PMID 31198409, 2019). "It has been reported that DLL4 is highly expressed in tumor-associated endothelial cells in colorectal cancer, suggesting that DLL4 is involved in modulating NOTCH signaling in colorectal cancer cells by heterotypic cell interactions." (PMID 24244701, 2013). "In colorectal cancer, DLL4 expression by tumor-associated macrophages has also been reported." (PMID 29636067, 2018). "DLL4 is known to be highly expressed in cancer-associated endothelial cells in colorectal cancer." (PMID 29104587, 2017). "For example, DLL4 expressed by endothelial cells was shown to activate Notch signaling via Notch3 in T cell acute lymphatic leukemia and via Notch1 in colorectal cancer." (PMID 39951484, 2025). "Studies in other disease states, including neonatal pulmonary hypertension and colorectal cancer, have identified a relationship with metformin and the downregulation of Dll4." (PMID 39518910, 2024). "In human colorectal cancer, inhibition of the Notch/DLL4/Hes pathway significantly inhibited angiogenesis." (PMID 36428773, 2022). "Jag2 was the most frequently observed ligand that was overexpressed in 52%, while a higher expression of Jag1, Dll1, Dll3, and Dll4 was found in 26%, 25%, 25%, and 39% colorectal cancers, respectively." (PMID 32211044, 2020). "Our aim was to evaluate the expression and dissect the functions of Dll4 in the ApcMin/+ model of colorectal cancer." (PMID 28086833, 2017). "In the current study, cancerous and stromal DLL4 expression were found in 49% and 23% of gastric cancer patients, which lower than that of colorectal cancer." (PMID 23898884, 2013). "Moreover, DLL4 is strongly expressed in renal cell carcinoma, stomach cancer, colorectal cancer, and metastatic breast cancer." (PMID 36428773, 2022). "Interestingly, results from this study also demonstrated that endothelial DLL-4 had the potential to induce colorectal cancer cell migration via Notch3 and Asef." (PMID 29104587, 2017). "Moreover, Dll4 expression may influence the sensitivity of endothelial cells to anti-VEGF therapy, with potential implications for the use of bevacizumab and novel anti-Dll4 antibodies in colorectal cancer." (PMID 19844231, 2009). "Circ‐NSD2 upregulates JAG1 in colorectal cancer, while circ_0006476 modulates DLL4 in atherosclerosis, illustrating how circRNAs regulate Notch ligands to amplify pathway activity across diseases." (PMID 40761890, 2025). "In addition to JAG1 and DLL4, the JAG2/NOTCH pathway also exerts a cancer-promoting effect in colorectal cancer cells, as JAG2 knockdown in colorectal cancer cells inhibits their expression of CD133, decreasing in a similar manner their ability to form spheroids and to induce metastasis." (PMID 37860822, 2023).
pancreatic cancer (15 papers, 2016 to 2023). "The studies demonstrated that VNARs can specifically bind to DLL4 with high affinity and are preferentially internalized by pancreatic cancer cell lines and endothelial cells that express DLL4." (PMID 37755109, 2023). "The combination of anti-DLL4 and gemcitabine had additive antitumor activity in pancreatic cancer xenograft models and delayed tumor recurrence after termination of gemcitabine treatment targeting DLL4 both in tumor and in stroma/vasculature." (PMID 34680255, 2021). "Two trials evaluating the combinations of gemcitabine (±protein-bound paclitaxel) and anti-DLL4 demcizumab for the treatment of advanced pancreatic cancer have been registered (NCT01189929 and NCT02289898)." (PMID 34680255, 2021). "Mullendore and coauthors observed overexpression of Notch ligands, predominantly Jag2 and Dll4 that were observed in 90% and 50% pancreatic cancer cell lines, respectively." (PMID 32211044, 2020). "Not only VEGF but DLL4 is also known to impair efficient delivery of anti-cancer drugs and to enhance chemoresistance in pancreatic cancer model due to induction of defective tumor angiogenesis." (PMID 33383646, 2020). "Suppression of FOXC1 decreased the levels of angiogenic markers VEGFR2 and DLL4 in pancreatic cancer cells." (PMID 29976975, 2018). "In this regard, a humanized anti-Dll4 antibody, demcizumab, is currently under evaluation in three Phase 1b studies on pancreatic cancer, CRC, and NSCLC98." (PMID 29062084, 2017). "The OMP-21M18, an anti-Delta-like ligand 4 (DLL4) is further been tested for inhibiting Notch-signaling in pancreatic cancer." (PMID 31656694, 2016). "Treatment with either human or mouse anti-Dll4 delayed pancreatic tumor recurrence following termination of gemcitabine treatment, and the two together produced an additive effect, suggesting a novel therapeutic approach for pancreatic cancer treatment through antagonism of DLL4/Notch signaling." (PMID 35406423, 2022). "Accordingly, in another model of pancreatic cancer, DAPT restrained the effects caused by DLL4-induced Notch activation, and pre-treatment with a high dose of DAPT abrogated DLL4/Notch-induced chemoresistance led to the activation of apoptosis and reduced the CSC pool." (PMID 34680255, 2021). "Besides, leptin is reported to induce the expression of Notch1-4, JAG1 and DLL4 in pancreatic cancer cells." (PMID 34588926, 2021). "Many previous studies showed that Dll4 expression were mostly found on the endothelial cells and it was considered as the mediator of Notch activation of angiogenesis in many cancers such as breast, colon, and pancreatic cancers." (PMID 26766040, 2016). "The most promising approach inhibiting this interaction so far involves a soluble EphB4 ECD conjugated to human serum albumin (EphB4-ECD-HSA), this has shown anti-angiogenic effects on pancreatic tumours in Rip1-Tag2 mice, which could be improved with Dll4-Notch blockade using Dll4-ECD-Fc." (PMID 26620208, 2016). "(iii) MEDI0639, an anti-Dll4 mAb, was tested on clinical trials for solid tumors, and (iv) demcizumab, an anti-Dll4 mAb, was clinically tested in non-small cell lung cancer (NSCLC), pancreatic cancer, primary peritoneal carcinoma, and other solid tumors." (PMID 37131214, 2023). "Delta-like ligand 4 (DLL4) is prone to overgrowing tumors, which is a good target for pancreatic cancer." (PMID 34066890, 2021). "Also, the pancreatic cancer dataset in TCGA indicates that DLL4, NOTCH1, NOTCH2, and NOTCH3 levels do not affect survival." (PMID 35673567, 2022).